AVP (arginine vasopressin)
Diseases named in the same sentence as AVP in open-access papers (continued):
Sharing a sentence is not in itself a finding about the gene and the disease.
Sepsis (43 papers, 2006 to 2025). Sepsis is defined as life-threatening organ dysfunction caused by a dysregulated host response to infection. "In CLP-treated animals, sepsis caused massive apoptosis of vasopressinergic neurons and impaired secretion of arginine vasopressin (AVP) in the hypothalamus were found to be closely associated with microglia activation and BBB leakage." (PMID 36530954, 2022). "Hence, impaired AVP which plays the role of antidiuretic and vasoconstrictive effects secretion may be the cause of hypotension shock in sepsis patients." (PMID 36530954, 2022). "In adults, several studies have evaluated the usefulness of copeptin in the diagnostic pathways of AVP-related diseases, as well as its potential role as prognostic marker in some clinical conditions such as acute myocardial lesions, renal and heart failure, stroke, and sepsis." (PMID 32809080, 2021). "Using a model to simulate the physiological, sepsis-related, and therapeutic AVP levels in plasma, we analysed how AVP and ClB affect PMN activities, including reactive oxygen species (ROS) production, NETosis, antigen expression, and migration." (PMID 40141155, 2025). "The Surviving Sepsis Campaign guidelines suggest adding arginine vasopressin (AVP) when norepinephrine (NE) doses reach 0.25–0.50 μg/kg/min in septic shock patients." (PMID 40299108, 2025). "It is therefore unsurprising that the PMNs with an AVP concentration corresponding to the situation during sepsis, in which the function of the PMNs is altered according to the literature, demonstrated restricted migration." (PMID 40141155, 2025). "Although not statistically significant in the present work, this result is consistent with studies in sepsis, where AVP decrease catecholamine needs." (PMID 38716382, 2024). "In patients with sepsis, combination of vasopressor therapy (e.g., catecholamine + arginine vasopressin) yields to better outcome for refractory shock." (PMID 36937900, 2023). "Several studies has shown that sepsis induces a depletion of plasmatic levels of AVP and a downregulation of angiotensin receptors in vascular bed56,57." (PMID 35790848, 2022). "Copeptin, a 39-amino acid glycopeptide, has been investigated as a direct marker of AVP secretion in various cerebrovascular diseases as well as myocardial infarction, pulmonary diseases, shock, and sepsis." (PMID 33806226, 2021). "“AVP impairment” refers to the inappropriate decrease of AVP concentration seen in the late phase of a sepsis or endotoxemia model despite the persistent hypotension that can lead to shock and eventually to death." (PMID 33430014, 2021). "Here, we report first time that modulation of peroxynitrite significantly reduced AVP requirements and improved net fluid balance using a well-characterized large animal translational model of sepsis and septic shock in an ICU setting." (PMID 31512009, 2019). "The large reduction in CO caused by TP is in accord with similar effects seen in this model of sepsis with AVP, and the well established ability of AVP to sensitize the arterial baroreflex, thus causing a greater fall in CO and HR for a given rise in pressure." (PMID 22355305, 2012). "On the other hand, AVP was closely associated with cortisol baseline in our study, but only in non-septic ICU patients, further suggesting distinctive stress pathways in sepsis." (PMID 20615266, 2010). "Arginine vasopressin (AVP) is recommended by the Surviving Sepsis Campaign to 'be subsequently added to norepinephrine' in volume- and catecholamine-refractory septic shock." (PMID 21054850, 2010). "Arginine vasopressin (AVP) is increasingly used to treat sepsis-related vasodilation and to decrease catecholamine requirements." (PMID 17032443, 2006). "If the hypothesis that reduced migration contributes to the development of sepsis is valid, early AVP administration may potentially prevent the initial reduction in migration and thereby facilitate more effective pathogen control." (PMID 40141155, 2025).
Sepsis (continued). "The results therefore indicate that the AVP concentration, which corresponds to the phase of sepsis, may initially reduce the migration potential of PMNs." (PMID 40141155, 2025). "Notably, while our experimental AVP concentration series showed a dose-dependent decrease in PMN migration, the sepsis-associated AVP levels led to a significantly stronger migration impairment than that expected from our in vitro data." (PMID 40141155, 2025). "To date, AVP levels have only been investigated in humans and modelled septic shock in cross-section, and longitudinal effects on AVP circadian rhythms are currently unknown, likely due to the persistently low level of AVP seen beyond early sepsis." (PMID 39968295, 2025). "This would lend support to the theory that the early administration of AVP at the onset of sepsis may prove beneficial to patients." (PMID 40141155, 2025). "An AVP concentration which corresponds to sepsis may act as a trigger for this inhibition of PMN function." (PMID 40141155, 2025). "Given that arginine vasopressin (AVP) is both an endogenous hormone and a potential therapeutic option in sepsis, it may play a pivotal role in the pathophysiology of diseases such as sepsis." (PMID 40141155, 2025). "The concentrations of AVP employed were meticulously selected to optimally represent disparate AVP plasma concentration states, encompassing a healthy physiological state, the pathological state of sepsis, and the state under continuous AVP-infusion administration." (PMID 40141155, 2025). "While the SNS, RAAS and AVP all constitute pivotal adaptive responses to stress, there is a compelling inclination to hypothesize that excessive and prolonged activation during sepsis may transition into a maladaptive state, eliciting adverse effects." (PMID 38799155, 2024). "Moreover, SARS-CoV-2 respiratory infection resembles other infectious conditions and sepsis, where AVP/copeptin is released as a stress-adapting and homeostatic hormone to maintain the euvolemic state, blood pressure with persevered renal functions." (PMID 35350852, 2022). "High doses of AVP were required to partially attenuate the sepsis-induced hypotension." (PMID 31512009, 2019). "This study tested the hypothesis that adjunct therapy with peroxynitrite decomposition catalyst (WW-85) would reduce arginine vasopressin (AVP) requirements during sepsis resuscitation, using ovine sepsis model." (PMID 31512009, 2019). "To test our hypothesis, we have tested the effects of WW-85, a novel peroxynitrite decomposition catalyst, as an adjunct therapy to titrated AVP in our well-characterized ovine MRSA-induced sepsis model." (PMID 31512009, 2019). "In this study, we hypothesized that excessive formation of peroxynitrite may cause a vascular hypo-responsiveness to AVP, and its pharmacological modulation could potentially be beneficial in the treatment of MRSA-induced sepsis." (PMID 31512009, 2019). "Patients with sepsis secondary to medical (vs. surgical) conditions have higher mortality, which may influence AVP response." (PMID 29511951, 2018). "An adjunctive AVP to norepinephrine infusion exhibits a favorable impact on renal function without deleterious effects on the liver and intestine in a porcine model of experimental sepsis when compared with norepinephrine infusion alone." (PMID 22283426, 2012). "Even so, we analyzed NO because it is considered one of the major factors responsible for refractory hypotension in sepsis, has its concentration increased after LPS injection, and appears to play a key inhibitory role in AVP released during endotoxemia, leading to hypotension." (PMID 23137350, 2012). "The major finding of this study was that AVP infusions in pigs with experimental sepsis at a dose of 0.5 mU.kg-1kg-1min-1 supplemented with norepinephrine improved renal function without deleterious effects on the liver and intestine when compared with norepinephrine infusion alone." (PMID 22283426, 2012).
Sepsis (continued). "Copeptin, a stable moiety of pre-pro-AVP is also considered as a valuable marker of severe sepsis." (PMID 20615266, 2010). "In addition, it has been reported that a highly selective V1 agonist (FE 202158) markedly reduced vascular leakage and mortality in experimental sepsis as compared with AVP." (PMID 19664253, 2009). "Copeptin concentrations mirror that of AVP and are also elevated in sepsis and septic shock." (PMID 18252006, 2008). "Copeptin is co-released with arginine vasopressin (AVP) in the hypothalamic stress response and is elevated in conditions such as sepsis, myocardial infarction, or stroke." (PMID 39056779, 2024). "The findings of these studies are compatible with glucocorticoid-receptor-ligand-binding-induced inhibition of pituitary processing of POMC into ACTH and with preserved CRH/AVP-driven expression of POMC, resulting in elevated circulating POMC levels in sepsis." (PMID 33593393, 2021). "In the mice, sepsis was found to acutely, though transiently, increase hypothalamic expression of CRH and AVP, followed by an upregulation of both CRH and AVP receptor expression at the pituitary level." (PMID 33593393, 2021). "In acute sepsis-induced critically ill mice (1-day sepsis group), paraventricular mRNA expression of both CRH and AVP was increased as compared with healthy controls (p = 0.04 and p = 0.03, respectively)." (PMID 33593393, 2021). "In mice, sepsis acutely increased hypothalamic mRNA of CRH (p = 0.04) and AVP (p = 0.03) which subsequently normalized." (PMID 33593393, 2021). "In prolonged septic mice (7-day sepsis group), mRNA expression of CRH and AVP was comparable to those of healthy control mice (both p > 0.05)." (PMID 33593393, 2021). "Indeed, low-dose AVP infusion is helpful to restore vascular tone, with catecholamine-sparing ability in septic patients, and additional beneficial effects have been observed with selepressin (a selective V1A receptor agonist) in both a relevant preclinical model of sepsis and septic shock patients." (PMID 29347994, 2018). "This study aimed at investigating the synthesis of corticotropin-releasing hormone (CRH) and vasopressin (AVP) by parvocellular neurons and the antehypophyseal expression of ACTH in human septic shock and in an experimental model of sepsis." (PMID 22073145, 2011). "This suggests a possible reset of sepsis-induced vascular V1aR down-regulation through the GRE receptor gene, and resurfaces a complex and often questioned link between AVP and corticosteroids, which is essentially disturbed in critical illness." (PMID 20615266, 2010). "This study examines how different concentrations of arginine vasopressin (AVP) and its preservative chlorobutanol (ClB) impact the immune functions of human polymorphonuclear neutrophils (PMNs), which are crucial in the immune response, particularly in sepsis." (PMID 40141155, 2025). "At physiological AVP levels, PMN migration showed no reduction, while the sepsis-associated AVP levels initially reduced migration before returning to the baseline or even increasing." (PMID 40141155, 2025). "It is notable that the migration of the PMNs incubated with the AVP plasma concentration reflective of sepsis conditions (AVP/ClB 12.4) was not in line with the expectations “higher AVP concentration results in lower migration”." (PMID 40141155, 2025). "However, they rarely assessed concomitantly the expression of AVP and CRH and their respective receptors as well as relationships between HPA activation and the severity of sepsis." (PMID 22073145, 2011). "In conclusion, our study provides evidence that an adjunctive AVP infusion to norepinephrine in a porcine model of experimental sepsis improves renal function without deleterious effects on intestine and liver functions when compared with norepinephrine administration alone." (PMID 22283426, 2012).
Sepsis (continued). "Indeed, arginine-vasopressin (AVP) heightens hypothalamic sensitivity to corticotrophin-releasing hormone (CRH), thereby increasing ACTH release and cortisol production, and improves hemodynamics during sepsis." (PMID 20615266, 2010). "The explanation for the divergent findings of AVP effects on various systemic vascular beds is not known, and whether the vasoactive response to AVP is fundamentally different in sepsis and cardiac ischemia is also not clear." (PMID 18291025, 2008). "Interestingly, a recent study in animals demonstrated that the combined infusion of NE and AVP improves hemodynamic variables compared with NE alone during sepsis, but not during cardiopulmonary resuscitation." (PMID 16677425, 2006). "It has been shown that LPS down-regulates the mRNA coding for AVP and CRH antehypophyseal receptors; however,the effect of prolonged experimental sepsis on these receptors has not been assessed yet." (PMID 22073145, 2011). "The Surviving Sepsis Campaign Guidelines 2021 recommend norepinephrine (NE) as the first-line vasopressor for septic shock; for patients with inadequate mean arterial pressure (MAP) < 65 mmHg, arginine vasopressin (AVP) should be added rather than increasing the NE dose." (PMID 41029879, 2025). "In the context of sepsis, arterial underfilling arising from systemic inflammation-induced arterial vasodilation serves as a robust trigger for the activation of the sympathetic nervous system (SNS), the renin–angiotensin–aldosterone axis (RAAS), and the non-osmotic release of vasopressin (AVP)." (PMID 38799155, 2024).
nephrogenic diabetes insipidus (41 papers, 2007 to 2026). Nephrogenic diabetes insipidus (NDI) is characterized by polyuria with polydipsia, recurrent bouts of fever, constipation, and acute hypernatremic dehydration after birth that may cause neurological sequelae. "AVP resistance (AVP-R, formerly called nephrogenic diabetes insipidus), is a urinary concentration disorder caused by reduced responsiveness to AVP due to vasopressin V2R dysfunction in the renal collecting ducts." (PMID 39847311, 2025). "Lithium is an effective mood stabilizer but may cause nephrogenic diabetes insipidus (NDI) by impairing the renal collecting duct response to arginine vasopressin (AVP)." (PMID 41948060, 2026). "Hypercalcemia can result in arginine vasopressin resistance (nephrogenic diabetes insipidus) and is an important differential in the evaluation of patients with hypotonic polyuria-polydipsia syndrome." (PMID 40123924, 2025). "Nephrogenic diabetes insipidus (NDI) is defined as the inability of the kidney to concentrate urine owing to the insensitivity of the distal nephron to the antidiuretic hormone, arginine vasopressin (AVP)." (PMID 40003297, 2025). "We also excluded the possibility of arginine vasopressin resistance (AVP-R, previously ‘nephrogenic diabetes insipidus’) caused by a loss-of-function mutation in the arginine vasopressin receptor 2 gene (AVPR2)." (PMID 41347136, 2025). "Nephrogenic diabetes insipidus (NDI) is characterized by the inability of the kidneys to respond to the hormone arginine vasopressin (AVP), leading to the failure of concentrating urine." (PMID 41393191, 2025). "Nephrogenic diabetes insipidus (NDI) is a rare hereditary disorder characterized by renal resistance to arginine vasopressin (AVP), resulting in the kidneys' inability to concentrate urine." (PMID 40806548, 2025). "The term "Nephrogenic Diabetes Insipidus" was coined to describe a clinical presentation akin to the syndrome of inappropriate ADH secretion but with undetectable levels of AVP." (PMID 38707045, 2024). "Nephrogenic Diabetes Insipidus (NDI) is a water balance disorder that is characterized by an inability to concentrate urine in response to the antidiuretic hormone arginine vasopressin (AVP)." (PMID 37674034, 2023). "Nephrogenic diabetes insipidus (NDI) is characterized by a normal physiologic release of AVP in response to an increase in plasma osmolarity, which, however, does not translate into subsequent hypertonic urine." (PMID 35678906, 2022). "Nephrogenic diabetes insipidus (NDI) is a group of diseases characterized by inability to concentrate urine in response to arginine vasopressin (AVP)." (PMID 29394883, 2018). "This suggests that a therapeutic trial with the standard dose of desmopressin is important to differentiate partial CDI, partial nephrogenic diabetes insipidus, and primary polydipsia, if measurements of AVP and copeptin are limited." (PMID 27118970, 2016). "This regulation is lost in patients whose nephron is unable to respond to AVP (nephrogenic diabetes insipidus) or affected by sustained AVP secretion and water retention (SIADH)." (PMID 26620256, 2015). "Arginine vasopressin (AVP) resistance (AVR) (formerly known as nephrogenic diabetes insipidus) by definition is a congenital or acquired defect in the distal and collecting tubules that results in insufficient urine concentration due to insensitivity to AVP." (PMID 41598788, 2026). "X-linked nephrogenic diabetes insipidus (X-linked NDI, MIM: 300538) is a rare X-linked recessive disease characterized by the inability of the kidney to concentrate urine in response to the antidiuretic hormone arginine-vasopressin (AVP)." (PMID 38254165, 2024). "Lithium treatment is one of the major causes of the acquired form of nephrogenic diabetes insipidus (NDI), a clinical syndrome in which the kidney is unable to concentrate urine despite normal or elevated concentrations of the antidiuretic hormone arginine vasopressin." (PMID 27713354, 2010).
nephrogenic diabetes insipidus (continued). "Here, we will focus on the nephrogenic diabetes insipidus (NDI), which can be seen as a renal resistance to vasopressin (AVP), the antidiuretic hormone." (PMID 35909256, 2023). "Nephrogenic diabetes insipidus (NDI), congenital or acquired, is characterized by failure to concentrate urine despite stimulated by normal or elevated arginine vasopressin (AVP) levels." (PMID 33804115, 2021). "Mutations of either AVPR2 or AQP2 result in a genetic disease known as nephrogenic diabetes insipidus, which is characterized by the lack of responsiveness of the collecting duct to the antidiuretic action of AVP." (PMID 29125546, 2017). "There is a need for novel oral antidiuretics to treat diseases, such as pituitary diabetes insipidus and nephrogenic diabetes insipidus; however, investigations for compounds other than the typically used arginine vasopressin (AVP) or desmopressin are lacking." (PMID 22494818, 2012).